NEAT1 (nuclear paraspeckle assembly transcript 1)
Diseases named in the same sentence as NEAT1 in open-access papers (continued):
Sharing a sentence is not in itself a finding about the gene and the disease.
breast cancer (continued). "Based on bioinformatics and experimental analyses, lncRNA NEAT1 have a significant down-regulation in the breast cancer samples with tumor size lower than 2 cm." (PMID 35581633, 2022). "Another highly represented in tumors and actively studied lncRNA NEAT1 (nuclear-enriched abundant transcript 1) was regulated in four types of cancer: breast cancer, hepatocellular carcinoma, nasopharyngeal carcinoma, and malignant thyroid nodules." (PMID 36362406, 2022). "Sequencing of large cohorts of breast cancer tissue has revealed recurrent mutations in long non-coding genes including MALAT1 and NEAT1." (PMID 36153537, 2022). "LncRNA NEAT1 as a significantly dysregulated RNA in the breast cancer and gastric cancer patients have significant interactions with the hub coding (MTRNR2L8) and non-coding RNAs (lncRNA XIST and hsa-miR-612)." (PMID 35581633, 2022). "Based on the ENCORI and data analysis, NEAT1 has a significant down-regulation in breast cancer (FC: 0.73, FDR: 0.015) and gastric cancer (FC: 1.81, FDR: 0.0016)." (PMID 35581633, 2022). "Specifically, NF-κB, OCT4, HIF-2a, and c-Myc can promote the transcription of NEAT1 in pancreatic cancer, lung cancer, breast cancer, and colorectal cancer, respectively." (PMID 36011001, 2022). "For validation of mentioned results about the expression of NEAT1, the TCGA data analysis was performed on the breast cancer RNA-seq dataset." (PMID 35581633, 2022). "Likely, lncRNA NEAT1 expression was upregulated in breast cancer tissues, and its inhibition in SKBR3 cells impaired cell proliferation by sponging miR-410-3p and subsequently downregulating cyclin D1 (CCND1)." (PMID 36613528, 2022). "The expression of NEAT1 is elevated in breast cancer cell lines, including MCF-7, MDA-MB-453, MDA-MB-231, and SKBR3 cells, compared with normal mammary epithelial cells such as MCF-10A." (PMID 36011001, 2022). "Studies have shown that NEAT1 contributes to the progression of many cancers, including breast cancer, lung cancer, hepatocellular carcinoma, ovarian cancer, and prostate cancer." (PMID 36011001, 2022). "Nevertheless, for the first time, we find a biological interaction between hsa-miR-612 and NEAT1 that can have significant effects on breast cancer and gastric cancer development." (PMID 35581633, 2022). "Further investigations about NEA1 and correlated mRNAs, lncRNAs, and microRNAs – specially the mentioned RNAs in this study – can lead the researchers to more clear information about the role of NEAT1 in the breast cancer and gastric cancer." (PMID 35581633, 2022). "High expression of NEAT1 have a correlation with the lower survival rate of breast cancer samples and higher survival rate of gastric cancer patients." (PMID 35581633, 2022). "NEAT1 displayed multiple function in regulating microRNA that it not only sponged miR-133b to promote migration and invasion of breast cancer cells, but also inactivated miR-101 to play potential oncogene in breast cancer." (PMID 36262350, 2022). "Recently, a direct HSF1-dependent up-regulation of NEAT1-1 and NEAT1-2 lncRNAs was described in human breast cancer MCF7 cells submitted to a mild 30-min heat shock at 43 °C followed by a recovery period of 2 h at 37 °C." (PMID 35456403, 2022). "The lncRNA NEAT1 (Nuclear Enriched Abundant Transcript 1) has been found deregulated in several human cancers including breast cancer." (PMID 36182907, 2022). "Transcriptional profiling, phenocopy and rescue experiments identified the short isoform of the lncRNA NEAT1 as a molecular trigger for ALYREF effects in breast cancer." (PMID 35776213, 2022). "ALYREF and SRSF1 can also prolong the half-life of NEAT1, facilitating the progression of breast cancer and glioma, respectively." (PMID 36011001, 2022). "In breast cancer, NEAT1 can bind and form a scaffold bridge for the assembly of phosphoglycerate kinase (PGK), phosphoglycerate mutase (PGAM), and enolase (ENO), elevating glycolysis and cancer metastasis." (PMID 36011001, 2022).
breast cancer (continued). "In this study, we aimed to evaluate the differences in the expression level of NEAT1 in the high-throughput breast cancer and gastric cancer datasets and the human GC and BC samples of the Isfahan population." (PMID 35581633, 2022). "In breast carcinoma, lncRNA nuclear enriched abundant transcript-1 (NEAT1) promoted tumor cell proliferation, migration, invasion and metastasis via miR-141-3p sponging and KLF12 upregulation." (PMID 35966580, 2022). "Power analysis was carried out to assess the diagnostic value of PVT1, HOTAIR, NEAT1, MALAT1, PAI-1, and OPN in breast cancer." (PMID 33670447, 2021). "Nuclear enriched abundant transcript 1 (NEAT1) has been shown to cause breast cancer progression by a feedback loop with STAT3, and miR-124 has been shown to inhibit NEAT1." (PMID 34488773, 2021). "The precise implication of PVT1/PAI-1 and MALAT1, NEAT1/OPN/HOTAIR networks in breast cancer development is still unclear." (PMID 33670447, 2021). "NEAT1 promotes the proliferation, migration, and metastasis of human breast-cancer cells by inhibiting miR-146b-5p expression." (PMID 34683909, 2021). "The expression of NEAT1 was markedly decreased in MIR3613 deletion group and its high expression tended to be associated with prolonged survival in breast cancer patients." (PMID 33494814, 2021). "The current study revealed that the serum expression of NEAT1 was significantly lower in the breast cancer patients compared to the fibroadenoma patients and the control subjects." (PMID 33670447, 2021). "In this section, we summarize the roles of the NEAT1/miRNA/target axis in reproductive system tumors, including breast cancer, ovarian cancer, cervical cancer, endometrial carcinoma, and prostate cancer." (PMID 34512157, 2021). "In this study, we analyzed the serum expression levels of lncRNAs PVT1, HOTAIR, NEAT1, and MALAT1, and their associated proteins, PAI-1, and OPN, in breast cancer patients compared to fibroadenoma patients and healthy subjects." (PMID 33670447, 2021). "The significance of serum PVT1, HOTAIR, NEAT1, MALAT1, PAI-1, and OPN levels as potential diagnostic biomarkers for breast cancer was assessed using a ROC curve." (PMID 33670447, 2021). "The serum level of PVT1 was significantly higher in breast cancer patients than in the controls, while that of NEAT1 was significantly lower in breast cancer patients compared to controls and fibroadenoma patients." (PMID 33670447, 2021). "In contrast, we observed the opposite effect with NEAT1_2 which was significantly upregulated, suggesting that eNEMAL regulates the NEAT1 isoform switch in MCF7 breast cancer cells." (PMID 34019552, 2021). "We divided all breast cancer patients from TCGA into two groups, based on the median expression value of NEAT1–ZFX–miR-138-5p." (PMID 33987091, 2021). "Altogether, we demonstrated that an eRNA transcribed from a MALAT1 enhancer regulates NEAT1 isoform expression, implicating the MALAT1–20 kb enhancer and its transcript eNEMAL in co-regulation of MALAT1 and NEAT1 in response to hypoxia in breast cancer cells." (PMID 34019552, 2021). "In the present study, we also measured the serum expression levels of HOTAIR, MALAT1, and NEAT1 as possible biomarkers of breast cancer." (PMID 33670447, 2021). "In the last few years, several studies indicating the involvement of NEAT1 in breast cancer have been published, and NEAT1 is closely related to different miRNAs." (PMID 34527584, 2021). "In breast cancer, lncRNA NEAT1 is highly expressed in breast cancer tissues and closely related to clinical stage, lymph node metastasis." (PMID 34659360, 2021). "Intriguingly, NEAT1 and its ceRNAs can also serve as prognostic markers for breast cancer, which further reveals that the constructed CCN has potential clinical applications." (PMID 33987091, 2021). "Depletion of NEAT1 inhibited cell growth, viability and morphology of breast cancer and Burkitt’s lymphoma cells." (PMID 33435206, 2021).
breast cancer (continued). "For instance, Yamei Pang found that the NEAT1/miR-124/STAT3 axis regulated the progression of breast cancer, and NEAT1 and STAT3 displayed similar functions as in our study." (PMID 33546665, 2021). "In breast cancer, NEAT1 serves as a ceRNA to modulate ZEB1 function by sponging hsa-miR-448, promoting cancer progression." (PMID 35008626, 2021). "In breast cancer cell lines and tissues, which predicted poor prognosis in breast cancer patients, miR-133b expression is inhibited by induced expression of the long non-coding RNA, NEAT1." (PMID 33297490, 2020). "NEAT1_1 showed a similar distribution among the PAM50 subtypes as total NEAT1, being highest in luminal A and luminal B breast cancers." (PMID 31992741, 2020). "For example, NEAT1 was reported to sponge miR-101 in non-small cell lung cancer, papillary thyroid carcinoma, hepatocellular carcinoma and breast cancer." (PMID 31868202, 2020). "For example, higher expression levels of NEAT1 were positively correlated with prognosis of breast cancer (BC) patients and NEAT1 knockdown suppressed N-cadherin expression while E-cadherin was upregulated." (PMID 32596382, 2020). "NEAT1 levels are elevated in hypoxic regions of breast cancer cell line xenografts, and skin tumors induced by genotoxic stress in mice, display increased NEAT1 expression and paraspeckle formation." (PMID 31992741, 2020). "In another report, NEAT1 is upregulated in breast cancer and Kaplan–Meier analysis indicated that high expression of NEAT1 is related to poor overall survival." (PMID 33292252, 2020). "Here, we report that NEAT1_2 expression correlates with HER2-positive breast cancers and high-grade disease." (PMID 31992741, 2020). "Hypoxia-induced NEAT1 expression accelerates the proliferation of breast cancer cells and inhibits their apoptosis." (PMID 32922184, 2020). "The lncRNA NEAT1 and MALAT1 are some of the most abundant cellular RNAs and the genes encoding them undergo recurrent mutation in breast cancer." (PMID 32527287, 2020). "The upregulation of NEAT1 has been documented in kidney cancer, ovarian cancer, lung cancer, breast cancer, and glioma cancers, contributing to the accurate prediction of clinical outcomes." (PMID 32148949, 2020). "In the future, experiments should be undertaken to determine the expression status of NEAT1 in these cells, as this would shed light on the function of NEAT1 in both postnatal mammary gland development and breast cancer." (PMID 31992741, 2020). "Recent studies have demonstrated that the lncRNA NEAT1 (nuclear enriched abundant transcript 1) is an oncogene that is overexpressed in multiple malignancies, including colorectal cancer, breast cancer, and leukemia." (PMID 32983133, 2020). "LncRNA nuclear paraspeckle assembly transcript 1 (NEAT1) was reported as an oncogene in breast cancer, osteosarcoma and hepatocellular carcinoma." (PMID 31868202, 2020). "In keeping with its oncogenic role, mutations in CpG islands within NEAT1 promoter have been reported in breast cancer, where increased levels of NEAT1—and paraspeckles—correlate with staging in HER+ patients." (PMID 33142861, 2020). "Ectopic expression of NEAT1 has been reported in many types of cancer including breast cancer, thyroid cancer, cholangiocarcinoma (CCA), hepatocellular carcinoma, ovarian cancer, colorectal cancer, pancreatic cancer, and osteosarcoma (OS)." (PMID 32296457, 2020). "A recent study has shown that NEAT1 promotes cell proliferation, migration and metastasis in breast cancer by inhibiting miR-146b-5p." (PMID 33585566, 2020). "Accumulating evidences suggested that NEAT1 plays crucial roles in carcinogenesis of multiple types of cancers, including breast cancer, colorectal cancer, nasopharyngeal cancer and gastric cancer." (PMID 33680941, 2020). "Hypoxia-induced NEAT1 expression accelerates the proliferation and inhibits the apoptosis of breast cancer cells." (PMID 32922184, 2020).
breast cancer (continued). "The expression of nuclear paraspeckle assembly transcript 1 (NEAT1) is required for the survival of breast cancer cells 15, and a high NEAT1 expression is correlated with the poor survival of patients with breast cancer." (PMID 32922184, 2020). "The activation of the transcription factor HIF-2 upregulates the expression of its downstream target lncRNA Nuclear Paraspeckle Assembly Transcript 1 (NEAT1) in breast cancer, resulting in an increased cell proliferation." (PMID 32992718, 2020). "Result showed that the tumor volume in the shNEAT1+cisplatin group was smaller than in the shNEAT1-treated group, indicating that NEAT1 suppression enhanced cisplatin sensitivity in breast cancer." (PMID 30894512, 2019). "The authors concluded that the BRCA1/NEAT1/miR‐129‐5p signaling axis contributes to breast cancer tumorigenesis." (PMID 30430751, 2019). "detected increased NEAT1 levels in diverse breast cancer cell lines compared to MCF‐10A cells (normal mammary epithelial cells)." (PMID 30430751, 2019). "We are the first to report that NEAT1 is upregulated in TNBC and expand our understanding on the role of NEAT1 in this malignant subtype of breast cancer." (PMID 30894512, 2019). "For example, NEAT1 promoted breast cancer growth by regulating miRNAs, such as miR-54824 and miR-44825." (PMID 30894512, 2019). "In breast cancer, high expression of NEAT1 was correlated with poor overall survival of ER+ breast cancer patients." (PMID 30894512, 2019). "NEAT1 was shown to compete with different RNA within the four breast cancer subtypes and thus exerting diverse regulatory functions on cell activities." (PMID 30430751, 2019). "Numerous studies focusing on NEAT1’s role in cancer biology indicate that this lncRNA is a crucial part of carcinogenesis as found in non-small lung cancer, breast cancer, hepatocellular carcinoma, ovarian cancer, and prostate cancer, just to name a few." (PMID 30717168, 2019). "By measuring the expression levels of NEAT1 in different breast cancer cell lines and normal breast cell line, we found NEAT1 levels were up-regulated in breast cancer cells compared with normal breast cells and negatively correlated with miR-133b levels." (PMID 31344855, 2019). "Consistent with our study, the expression levels of some abnormally expressed miRNAs in breast cancer were up- or down-regulated in response to NEAT1 knockdown or overexpression." (PMID 31344855, 2019). "Among 90 lncRNAs, NEAT1 was highly expressed in the blood samples of breast cancer patients than in NC." (PMID 30894512, 2019). "This suggests that increased NEAT1 expression can act as an oncogene (in breast cancer), promoting proliferation and metastasis of breast cancer." (PMID 31214487, 2019). "We further evaluated the expression of NEAT1 in paired breast cancer tissues and stratified into ductal carcinoma in situ (DCIS), luminal, HER2, and TNBC subtypes." (PMID 30894512, 2019). "Since 2016, a lot of research was done on NEAT1 contribution to breast cancer progression and several studies have shown a connection of this lncRNA with different miRNA." (PMID 30430751, 2019). "Several studies demonstrated that NEAT1 contributed to breast cancer progression, and although it is a classical nuclear lncRNA, some of the studies have shown a connection between NEAT1 and different miRNAs, such as miR-218, miR-448, miR-101 and miR-548." (PMID 31344855, 2019). "After inoculating the engineered MCF-7 breast cancer cells into the left abdominal mammary fat pad, it was found that overexpression of either NEAT1 or FOXN3 efficiently promoted lung metastasis in animal models." (PMID 31214490, 2019). "Knockdown of NEAT1 leads to reduced cellular growth and increased apoptosis of breast cancer cell lines." (PMID 30430751, 2019). "Upregulated NEAT1 expression increases breast cancer cell growth by targeting miR‐101, a miRNA which was shown to negatively correlate with NEAT1 expression levels." (PMID 30430751, 2019).
breast cancer (continued). "Overexpression of both FOXN3 and NEAT1 in breast cancer led to GATA3 expression impairment and strongly correlated with poor prognosis." (PMID 31003545, 2019). "In our study, we identified that NEAT1 expression was upregulated in the circulation of breast cancer patients and remarkably discriminated from normal controls." (PMID 30894512, 2019). "By now, only limited studies reported on the action of NEAT1 in breast cancer, and others focused on its implication as a hypoxia-induced lncRNAs and led to accelerated cellular proliferation and increased tumorigenesis." (PMID 30894512, 2019). "We also confirmed that lncRNA NEAT1 was up-regulated in breast cancer and inhibited the expression of miR-133b, and identified the mitochondrial protein translocase of inner mitochondrial membrane 17 homolog A (TIMM17A) that serves as the target of miR-133b." (PMID 31344855, 2019). "Increased cellular proliferation and clonogenic survival as well as decreased apoptosis of breast cancer cells are the outcome of hypoxia‐induced NEAT1 upregulation." (PMID 30430751, 2019). "To confirm the upstream regulatory effect of NEAT1 on miR-133b, we performed a rescue assay with breast cancer cells by overexpressing NEAT1 or miR-133b and NEAT1." (PMID 31344855, 2019). "As uncovered by reports, the increase in NEAT1 is related to the deteriorated prognosis of lung cancer, breast cancer, hepatocellular cancer, and colorectal cancer (abbreviated as CRC)." (PMID 30575330, 2019). "In conclusion, we found that NEAT1 was overexpressed in the circulation of breast cancer, especially TNBC." (PMID 30894512, 2019). "al. found that NEAT1 was highly expressed in breast cancer tissue, and the NEAT1 expression correlated to tumor size and lymph node metastasis." (PMID 31214487, 2019). "Some studies have shown that NEAT1 is an oncogene in various cancers, such as lung cancer, breast cancer, prostate cancer, colorectal cancer, and pancreatic cancer." (PMID 30185232, 2018). "On the other hand, BRCA1 inhibits NEAT1 expression through binding to its genomic binding site upstream of the NEAT1 gene in breast cancer." (PMID 30374364, 2018). "In gastric cancer, laryngeal squamous cell cancer, pancreatic cancer, oral squamous cell carcinoma, nasopharyngeal carcinoma and breast cancer, knockdown of NEAT1 via small interfering RNA (siRNA) inhibited cell proliferation." (PMID 30374364, 2018). "For example, KCNQ1OT1, MALAT1, XIST, and NEAT1 are experimentally confirmed breast cancer-related lncRNAs, which have been ranked 2nd, 11th, 12th, and 19th in the predicted list based on the model of DCSLDA, respectively." (PMID 30046354, 2018). "Bioinformatic analysis of sample-matched miRNA-seq and RNA-SeqV2 data of breast cancer from The Cancer Genome Atlas (TCGA) revealed that NEAT1 was overexpressed in luminal A, luminal B, HER2+, and basal-like (TNBC) tumors." (PMID 30545127, 2018). "Several studies reported that transcription factors such as hypoxia-inducible factor (HIF)-2 and RUNX1 bind to the locus of NEAT1 and induce its expression in breast cancer." (PMID 30374364, 2018). "LncRNA NEAT1 is highly expressed in breast cancer tissues and expression correlates with tumour size and metastatic potential." (PMID 29732012, 2018). "Along with its role in mammary gland development NEAT1 has also been observed to behave as an oncogene, by promoting proliferation and metastasis in breast cancer patients." (PMID 29732012, 2018). "The results showed that SNHG6 and NEAT1 were reversely expressed in breast cancer combined with primary lung cancer compared with primary breast or lung cancer." (PMID 28938549, 2017).